HIF1A (hypoxia inducible factor 1 subunit alpha)
Diseases named in the same sentence as HIF1A in open-access papers (continued):
Sharing a sentence is not in itself a finding about the gene and the disease.
tumor (continued). "Consistent with our hypothesis that highly glycolytic neutrophils lead to poorer PDAC prognosis, both human and OT mouse data show that tumor-infiltrating neutrophils express elevated levels of HIF-1α+, are highly glycolytic and thus may have a role in driving PDAC progression." (PMID 36614196, 2023). "Furthermore, our IHC staining results confirmed that PK5-RL-Gal-3C treatment could decrease the expression of HIF-1α in xenograft HCC tumor tissues in vivo." (PMID 36793021, 2023). "Tumor diversity seems to be triggered by hypoxia, evidenced by a high positive correlation between tumor diversity and hypoxia-induced genes, including hypoxia-inducible factor 1α (HIF1a) and the direct downstream target, vascular endothelial growth factor A (VEGFA)." (PMID 36980203, 2023). "Furthermore, a linkage between the critical tumor microenvironment hallmark with malfunction of the forementioned metastasis inhibition mechanism was presented, as demonstrated by repressed expression of PUS10 due to hypoxia and HIF-1A." (PMID 37596681, 2023). "Tumor cells release ROS into the tumor microenvironment and are detected by adjacent fibroblasts (CAFs), initiating the onset of stromal oxidative stress, autophagy, and mitophagy due to activating HIF-1α and VEGF that will ultimately contribute to angiogenesis." (PMID 36831498, 2023). "In addition, with the prolonged treatment of HepG2 cells with 20 μg/mL of the CXCL14 protein, the expression levels of pro-apoptotic genes BAK and BAX increased significantly, while the expression levels of tumor pro-proliferation genes HIF1A, mTOR and CDK1 decreased significantly." (PMID 37835641, 2023). "HIF-1α may contribute to tumor onset, while HIF-2α can mediate tumor formation and growth." (PMID 36724056, 2023). "The GSEA analysis showed that ESM1 overexpression was associated with the co-expression of VEGFα and HIF-1α and was closely related to the VEGFα signaling pathway; ESM1 may regulate CSCC micro-angiogenesis and tumor progression via interaction with VEGFα and HIF-1α." (PMID 37476182, 2023). "HIF1α staining of mouse tumor samples showed that JP1 significantly improved the intratumor microenvironment hypoxia under normoxic conditions, while under hypoxic conditions, intratumoral hypoxia was more severe and JP1 could not reverse the hypoxic state of the intratumor microenvironment." (PMID 37192004, 2023). "In summary, our data highlights the importance of HIF-1α expression and glycolytic status in modulating immune-cell metabolism and suggests that modulators of these metabolic pathways could be potential new targets to restrict tumor progression in PDAC." (PMID 36614196, 2023). "A possible explanation for such findings could be that HIF-1α expression is an early event in tumorigenesis, which is not hypoxia-related, but linked to alterations in tumor-suppressor genes and oncogenes." (PMID 37445908, 2023). "Moreover, HIF-1α, PD-1, and PD-L1 expression levels in tumor tissues decreased significantly." (PMID 37397393, 2023). "Hypoxia in tumor tissue can be reflected by direct measurement of tissue oxygen pressure through the microelectrode method or by detection of hypoxia-inducible factor 1α (HIF-1α) expression, or by imaging methods in vitro, such as by positron emission tomography (PET) with the hypoxia tracers." (PMID 36983693, 2023). "Hence, VEGFα/HIF-1α is a promising biomarker for targeting tumor angiogenesis." (PMID 37476182, 2023).
tumor (continued). "In addition, only HIF-1α expressing neutrophils were significantly increased in proportion in the tumor tissue compared to GLUT1+ and HK2+ neutrophils, highlighting that HIF-1α may have an important role in tumor progression." (PMID 36614196, 2023). "In all cases, cells with HIF-1α were immunohistologically shown to be grouped in specific areas of necrotic cells, so-called “hypoxic regions”, except for the chemotherapy alone and the bimodal therapy animal group, wherein only very few hypoxic cells were spotted all over the tumor." (PMID 38201461, 2023). "The regulation of long noncoding RNAs (lncRNAs) in HIF‐1α‐driven tumor development remains unclear." (PMID 37701531, 2023). "Furthermore, PVT1 contributes to tumor development by targeting miR-519d-3p/HIF-1A in PAAD." (PMID 36882663, 2023). "Moreover, repressing STAT3 and HIF-1α could mitigate the tumor-promoting role of TRIM14 in HCC cells." (PMID 37628777, 2023). "Therefore, the authors hypothesized that HIF1A overexpression might contribute to poor clinical outcomes by providing a growth advantage under hypoxic stress, accelerating tumor invasion and metastasis." (PMID 36994412, 2023). "Thus, during the hypoxia simulated by means of CoCl2 in patient-derived tumor primary cultured cells, the expression of genes HIF-1α and AhR changed unidirectionally, whereas AhR and CYP1B1 expressions were activated by the inducer (B[a]P) only during the hypoxic state of the cultured tumor cells." (PMID 37305351, 2023). "However, the HIF-1α inhibitor 2-ME2 abrogated the increase in VEGFA, MMP2, and MMP9 induced by GSTZ1 deficiency in orthotopic mouse models, revealing that inhibition of HIF-1α with 2-ME2 substantially reversed tumor growth, MVD, and progression in Gstz1-KO mice." (PMID 37906252, 2023). "Moreover, GSK3α-mediated tumor angiogenesis depended on HIF1α expression both in vitro and in vivo." (PMID 35292059, 2022). "In addition, some studies report HIF-1α as a tumor suppressor." (PMID 35267567, 2022). "In addition to HIF-1α-induced Beclin-1 activation, both HIF-1α and NFĸB also promote the expression of major EMT-associated transcription factors Snail, Slug, Twist1 and ZEB1/2, indicating a strong relationship between ROS and tumor progression." (PMID 35884592, 2022). "Therefore, activating the HIF-1α pathway is related to tumor invasion and poor clinical prognosis." (PMID 36319626, 2022). "Therefore, we can draw the hypothesis: MUC1 increases the uptake of glucose and the production of lactate through the HIF-1α signaling pathway, so that tumor cells can survive under hypoxic conditions." (PMID 35879749, 2022). "Therefore, inhibiting HIF-1α is considered as an effective strategy to restrain tumor growth." (PMID 36296726, 2022). "Therefore, we hypothesize that RBCK1 promotes tumor progression in ER-positive breast cancer by the HIF1α pathway." (PMID 36473847, 2022). "Excessive lactate production could promote angiogenesis and tumor vascularization through the induction of HIF-1α-stimulated VEGF increase, and dysregulated pH is also involved in chemotherapeutic drug resistance (e.g., vinblastine, doxorubicin, and paclitaxel)." (PMID 35992779, 2022). "They proposed that the level of HIF-1α may be used to predict tumor radioresistance." (PMID 36121548, 2022). "In addition, the present study demonstrates that the transient glycolytic switch in monocytes also induces the stabilization of HIF1α, which acts synergistically with autocrine cytokines to upregulate the sustained expression of CA12 on tumor-associated macrophages." (PMID 35362480, 2022).
tumor (continued). "In addition, tumor cells can increase angiogenesis by inducing the increase of vascular endothelial growth factor (VEGF) which is downstream of hypoxia-inducible factor 1α (HIF-1α) and PTHrP expression to form a blood-rich environment conducive to tumor growth." (PMID 36230816, 2022). "In addition, HIF-1α promotes tumour angiogenesis and VM and may be a prognostic biomarker for some tumours." (PMID 35669101, 2022). "Furthermore, the mRNA level of HIF1α under normoxia was also significantly enhanced in culture media-induced CAFs, indicating that tumor cells could significantly enhance the glycolytic rate of CAFs which might be achieved through a complex regulatory network." (PMID 36319992, 2022). "In addition, HIF-1α is also considered to be a protein essential for activating tumor growth." (PMID 35682354, 2022). "The HIF-1α knockdown cells caused lower rates of proliferation and migration; when these cells were transplanted into animals, they resulted in a 57% reduction in tumor size, not in the HIF-2α xenograft." (PMID 35592530, 2022). "Furthermore, in vivo studies have detected colocalization of HIF1A and PD-L1 in tumor cells." (PMID 35659268, 2022). "Therefore, we can speculate that there may be a mutual activation pathway between lncRNA H19 and HIF-1α, which regulates tumor growth under hypoxia through mutual promotion of expression." (PMID 36139386, 2022). "Therefore, HIF-1α has an important role in tumor growth and carcinogenesis." (PMID 36295510, 2022). "Moreover, LMP1-positive and HIF-1α-positive exosomes could increase cell migration and invasion, affecting tumor development." (PMID 35884611, 2022). "Similarly, some lncRNAs can be directly induced by HIF-1α and then promote tumor EMT progression." (PMID 36139386, 2022). "Notably, several researches have revealed that HIF1α inhibition could suppress tumor growth of ESCC and sensitize ESCC cells to therapeutic approaches." (PMID 35614065, 2022). "Although when the gene encoding HIF-1α was disrupted in the lung epithelium of a K-ras mutant mouse model (CC-LR), independent of COPD-like airway inflammation, the number of surface tumors in the mouse lung, tumor angiogenesis, and tumor cell proliferation were considerably reduced." (PMID 36338690, 2022). "Importantly, HIF-1α inhibition synergizes with anti–PD-1 therapy to inhibit tumor development." (PMID 35499071, 2022). "Additionally, CASQ2 upregulated HIF1α expression in both tumor cells and cocultured fibroblasts." (PMID 34743414, 2022). "Hence, we used the GEPIA dataset to analyze the correlation between HIF1α expression level and tumor pathological stage, including 17 tumors, while other tumors could not be shown in the GEPIA database." (PMID 35860430, 2022). "Targeting the HIF-1α/VEGFA axis could be a promising strategy against tumor angiogenesis." (PMID 35918758, 2022). "Moreover, PEDF can inhibit tumor angiogenesis by decreasing the expression of HIF-1α and VEGF." (PMID 36574366, 2022). "Finally, we found that FAM83A-AS1 knockdown could inhibit tumor growth and suppress the expression of HIF-1α and glycolysis-related genes in vivo." (PMID 35002507, 2022). "As transcription factors induced in tumor cells by hypoxic environmental stress, HIF-1α and HIF-2α could regulate a variety of downstream genes, thereby increasing the invasive ability of tumors and their resistance against standard radiotherapy and chemotherapy." (PMID 35629169, 2022). "Interestingly, ABCB1 is an HIF1A target gene, and HIF1A participates in the hypoxia-mediated multidrug resistance of tumor cells by inducing ABCB1 expression, reducing chemotherapeutic drug accumulation in tumor cells and inhibiting chemotherapy-induced apoptosis." (PMID 35659268, 2022).
tumor (continued). "Hypoxia-inducible factor-1α (HIF-1α), which controls glycolysis and pyruvate metabolism, triggers the expression of diverse genes regulating metabolic pathways, angiogenesis, DNA replication, the synthesis of proteins, tumour metastatic potential as well as resistance to therapy." (PMID 35328822, 2022). "However, when TACE induces tumor necrosis, it can also aggravate hypoxia at the tumor site, which leads to upregulation of hypoxia-inducible factor 1α (HIF-1α) and vascular endothelial growth factor (VEGF), thus resulting in tumor-associated angiogenesis, tumor recurrence and metastasis." (PMID 36202781, 2022). "In addition, PD-L1 expression on tumor cells is upregulated via HIF1A under hypoxia, and the effect of immune checkpoint inhibitors may be enhanced by HIF1A inhibitors." (PMID 35565252, 2022). "Regardless of the mechanisms of these changes (acquisition of new HIF-1α-dependent functional properties by tumor cells or enhancement of resistant clones), the cytological substrate that implements adaptation to antiangiogenic therapy is, first of all, the fraction of hypoxic tumor cells." (PMID 35054914, 2022). "Furthermore, hypoxic tumor cells surrounding fusion necrosis coexpress HIF1A and PD-L1." (PMID 35659268, 2022). "Future efforts will be necessary to clarify this opposite role of HIF-1α on regulating cell dormancy and re-awakening, with particular attention on the role exerted by the different microenvironmental composition between the primary tumor and the metastatic lesions." (PMID 35158815, 2022). "Based on these data, we proposed that given HIF1α expression is induced under hypoxic conditions, deficient PB1 not only activates AKT–mTOR and the glycolysis signalling pathways but also exerts a synergetic effect on HI1a expression, which collectively promote ccRCC tumour growth." (PMID 35672925, 2022). "In addition, HIF-1α was reported to be a key regulator in tumor-infiltrating NK cells." (PMID 35769460, 2022). "The interaction between lncRNAs and HIF-1α may greatly impact tumor progression." (PMID 35819532, 2022). "Lung endothelial cell dysfunction may represent evidence that pulmonary vascular remodeling in severe PH involves elements of abnormal angiogenesis similarly as observed in neoplastic cells, where HIF-1α is the key molecule in the angiogenesis control and tumor growth." (PMID 35870078, 2022). "However, recent studies have also suggested that HIF1A may function as a tumor suppressor during PDAC initiation, highlighting the dual function of this protein." (PMID 35440539, 2022). "However, RUNX1/ETO fusion protein interacts with HIF-1α for tumor progression." (PMID 36231060, 2022). "Treating DEN rats with GaNPs and low dose of γ-radiation significantly elevated Sirt-3 expression which may play a role in tumor suppression, mainly through mediating the suppression of hypoxia-inducible factor 1α (HIF-1α) and inhibiting mitochondrial ROS production." (PMID 35776276, 2022). "Moreover, GSK3α-mediated tumor angiogenesis relies on HIF1α expression both in vitro and in vivo." (PMID 35292059, 2022). "Importantly, S100A4(+)/HIF-1α(−) tumor cells were recruited along the surface of host preexisting vessels in vascular-rich areas of non-Ps perinecrotic lesions, whereas high VEGFA mRNA expression was found in S100A4(+)/HIF-1α(+) GBM cells in the adjacent areas." (PMID 35392912, 2022). "The accumulation of HIF-1α due to DOX induction in cells is caused by increased expression and activation of Signal transducer and activator of transcription 1 (STAT1) where this activation will stimulate the expression of iNOS and its NO synthesis in tumor cells." (PMID 35340325, 2022). "Therefore, we explored the role of HIF-1α in lactate-induced sEV release by tumor cells." (PMID 36531060, 2022).
tumor (continued). "HIF-1α is overexpressed in several cancer tissues including liver cancer, lung cancer, osteosarcoma, glioma, ovarian cancer, and renal cell carcinoma and regulates biological behaviors covering angiogenesis, tumor cell metabolism, and immune escape of tumor stem cells." (PMID 35528614, 2022). "In addition to being affected by the hypoxic tumour microenvironment, acidic pHe has been observed to regulate HIF1α and HIF2α levels under normoxic conditions in glioma cells, promoting cancer stem cell maintenance, highlighting the feedback regulation and crosstalk between hypoxia and low pHe." (PMID 35806388, 2022). "Next, we will classify and summarize the current HIF-1α-targeting inhibitor drugs according to their mechanism of action from the following aspects, aiming to provide clinical treatment ideas for reversing poor tumor progression by inhibiting HIF-1α production and accumulation." (PMID 36139386, 2022). "Thus, in the near future, multiple diagnostic assessments measuring or quantifying HIF-1α, CAIX, mTor or CD68/CD163 balance in tumor specimens and/or plasmatic samples might be proposed during the OTS patient journey to evaluate outcome risks." (PMID 35326631, 2022). "Therefore, the therapeutic strategy of suppressing hypoxia/HIF-1α in tumor tissues using NBO2 water may affect both radiation sensitivity and radiation-related side effects." (PMID 35743281, 2022). "As a result, HIF-1α and lincRNA-p21 form a positive feedback loop to promote glycolysis of HeLa cells, and it was also proved that lincRNA-p21 could significantly promote tumor growth in a mouse xenotransplantation model." (PMID 36124026, 2022). "Whether HIF-1α promotes tumor invasion and metastasis by activating YAP/TAZ is rarely reported." (PMID 35664561, 2022). "In addition, the combination of the HIF-1α inhibitor px-478 and the immune-checkpoint inhibitor enhances the cytotoxicity of T cells against tumor cells, which might be related to the blocking of the HIF-1α/LOXL2 signaling pathway." (PMID 36212414, 2022). "Therefore, a HIF1A-RRAGB-mTORC1 positive feedback loop exists in CRC to drive tumor progression, and circEXOC6B might antagonize the loop by binding to RRAGB." (PMID 35739524, 2022). "Finally, the growth of large, solid tumor microtissues on RGD-free HAGM cryogels, along with HA-mediated CD44 activation, is probably responsible for the overexpression of genetic markers for hypoxia and tumor aggressiveness, including HIF1α, WNT-11, BCL2, CD73, and VEGF." (PMID 35198956, 2022). "We found that apyrase and HIF-1α-siRNA caused significant reductions in the spheroid formation capacity of these tumor cells as well as reduced the expression of HIF-1α, indicating that apyrase and HIF-1α-siRNA both enhanced cisplatin sensitivity in 3D tumor models." (PMID 35236823, 2022). "Whether PPARγ agonists sensitize NSCLCs to chemotherapy and are of therapeutic benefit, or whether other Hif-1α-dependent signaling pathways might interfere in this tumor type, could be relatively easily answered from researchers’ long clinical experience with the use of PPARγ agonists." (PMID 35954274, 2022). "Analysis of tumor growth curve showed that cells expressing GSK3α + shnc grew faster than those expressing vector + shnc, while GSK3α promoting tumor growth could be inhibited by silencing of HIF1α." (PMID 35292059, 2022). "HIF-1α may be the source of signal transduction and a major determinant of tumor radiosensitivity." (PMID 36418890, 2022). "Interestingly, TAM-derived factors such as transforming growth factor-β could inhibit SDH in the tumor cells, which resulted in an accumulation of succinate and subsequent HIF1α stabilization." (PMID 36551845, 2022). "Besides promoting tumor cells to adapt to the hypoxic environment and proliferate, HIF-1α also functions as the master regulator of immune escape by transcriptionally upregulating multiple genes that suppress the innate and adaptive immune responses against cancer cells." (PMID 35805044, 2022).